MYOSLID (myocardin-induced smooth muscle lncRNA, inducer of differentiation)
Gene: Long non-coding RNA gene on chromosome 2 (207,165,961 to 207,253,323, forward strand). Ensembl gene ENSG00000229647.
Diseases named in the same sentence as MYOSLID in open-access papers:
MYOSLID is named in the same sentence as 13 diseases in open-access papers, as found by Europe PMC text mining. Sharing a sentence is not in itself a finding about the gene and the disease. The quoted sentences say what the papers report.
gastric cancer (10 papers, 2019 to 2025). A primary or metastatic malignant neoplasm involving the stomach. "In conclusion, we report a novel gastric cancer‐associated lncRNA MYOSLID and first discovered that lncRNA MYOSLID is a carcinogenic lncRNA that promotes cell proliferation and inhibits apoptosis in human GC via the miR‐29c‐3p‐MCL‐1 axis." (PMID 31497917, 2019). "For example, MYOSLID functions as a competing endogenous RNA (ceRNA) by acting as a molecular sponge for miR-29c-3p in gastric cancer." (PMID 40149492, 2025). "Many studies have reported MYOSLID as a prognostic factor for multiple cancers, such as head and neck squamous cell carcinoma, gastric cancer, and osteosarcoma." (PMID 39355236, 2024). "Han’s study found that MYOSLID plays a key role in the incidence and progression of gastric cancer through the MYOSLID-miR-29c-3p-MCL-1 axis." (PMID 35237659, 2022). "MYOSLID was correlated with tumor size, stage, invasion, and survival time in gastric cancer, and its knockdown inhibited tumorigenesis in mouse xenografts." (PMID 31969990, 2020). "Its overexpression, facilitated by MYOSLID’s sponging effect, enhances gastric cancer growth." (PMID 40149492, 2025). "MYOSLID (Myocardin-Induced Smooth Muscle LncRNA Inducer of Differentiation) is a newly identified lncRNA with critical implications in cancer biology, first recognized in gastric cancer." (PMID 40149492, 2025). "A previous study reported MYOSLID was considered as an oncogene for gastric cancer." (PMID 39355236, 2024). "Recent studies revealed that MYOSLID could promote the development of gastric cancer, osteosarcoma and head and neck squamous cell carcinoma." (PMID 36139524, 2022). "Similarly, MYOSLID could enhance the degree of malignancy by promoting the expression of MCL1 in gastric cancer." (PMID 35846431, 2022). "Furthermore, the role of MYOSLID in HNSCC and gastric cancer has been validated using a series of in vitro and in vivo experiments." (PMID 35846431, 2022). "In addition, qRT‐PCR analysis of lncRNA MYOSLID and miR‐29c‐3p in 75 gastric cancer tissues revealed a significant negative correlation between the expression levels of lncRNA MYOSLID and miR‐29c‐3p." (PMID 31497917, 2019).
head and neck squamous cell carcinoma (10 papers, 2019 to 2025). A squamous cell carcinoma that arises from any of the following anatomic sites: lip and oral cavity, nasal cavity, paranasal sinuses, pharynx, larynx, and salivary glands. "MYOSLID was identified as a lncRNA that promotes invasion and metastasis by modulating a partial epithelial-interstitial transformation procedure for head and neck squamous cell carcinoma." (PMID 36147735, 2022). "The previous research has indicated that MYOSLID was upregulated in the head and neck squamous cell carcinoma and contributed to tumor metastasis." (PMID 35846431, 2022). "In terms of partial epithelial-mesenchymal transition (p-EMT), MYOSLID expression in head and neck squamous cell carcinoma (HNSCC) was closely correlated with Slug, PDPN, and LAMB3, and is a key regulator of tumor cell survival." (PMID 34257164, 2021). "MYOSLID is involved in the advancement of head and neck squamous cell carcinomas (HNSCC) and osteosarcoma, and its mechanism of action is by promoting RAB13 expression by sponging microRNA-1286 or promoting invasion and metastases by regulating a part of the epithelial-mesenchymal transformation." (PMID 36280825, 2022). "The upregulation of long noncoding RNA (lncRNA) myocardin-induced smooth muscle lncRNA, inducer of differentiation (MYOSLID) was associated with the modulation of partial EMT, leading to metastasis and poor prognosis in head and neck squamous cell carcinoma (HNSCC)." (PMID 33207810, 2020).
osteosarcoma (6 papers, 2022 to 2025). A usually aggressive malignant bone-forming mesenchymal neoplasm, predominantly affecting adolescents and young adults. "MYOSLID was involved in the growth of osteosarcoma and amplifies the vascular smooth muscle differentiation program." (PMID 36226251, 2022). "MYOSLID promotes the progression of osteosarcoma through the miR-1286/RAB13 axis, and MYOSLID plays a key role in stomach neoplasm through the miR-29c-3p-mcl-1 axis, but it has not been reported in CC." (PMID 35087586, 2022). "RAB13 is a key promoter of cellular migration and invasion, and MYOSLID upregulates RAB13 by inhibiting miR-1286 activity, thereby enhancing the metastatic potential of osteosarcoma (OS) cells." (PMID 40149492, 2025). "MYOSLID-mediated overexpression of RAB13 further drives migration and invasion in osteosarcoma cells, highlighting its oncogenic role." (PMID 40149492, 2025).
colon cancer (3 papers, 2022 to 2025). "HCT15 cells exhibited the highest expression of MYOSLID, with a fold change of approximately 13.00 (p < 0.05) relative to other colon cancer cell lines." (PMID 40149492, 2025). "MYOSLID has been revealed to be highly expressed in colon cancer cell lines (RKO and HCT116) and accelerate the malignant activity of colon cancer cells." (PMID 39355236, 2024). "The activity of colon cancer cells was observably decreased following MYOSLID knockdown in HCT116 and RKO cell lines, which is similarly to other reports." (PMID 39355236, 2024). "Similar to other studies, our study showed MYOSLID promoted the proliferation of colon cancer cells, and overexpression of MYOSLID prognosticated poor prognosis in colon cancer patients." (PMID 39355236, 2024). "The upregulation of MYOSLID in tumor tissues indicates its potential role in reprogramming lipid metabolism, thereby affecting energy homeostasis with colon cancer cells, contributing to tumor progression, and potentially offering new avenues for individualized treatment strategies." (PMID 40149492, 2025). "Taken together, MYOSLID promoted cell proliferation and CS of colon cancer cells." (PMID 39355236, 2024). "Furthermore, MYOSLID, one of 3-CSRLs in the prognostic model, could dramatically regulate the proliferation and CS of colon cancer." (PMID 39355236, 2024). "Finally, we discovered that MYOSLID could influence the biological function and CS of colon cancer." (PMID 39355236, 2024).
colorectal cancer (3 papers, 2022 to 2025). A primary or metastatic malignant neoplasm that affects the colon or rectum. "We also identified the hub lncRNA MYOSLID in our model and preliminarily ascertained the potential mechanism underlying how it regulates the development of colorectal cancer." (PMID 36139524, 2022). "Experimental evidence revealed that MYOSLID is markedly upregulated in colorectal cancer cell lines, particularly in HCT15." (PMID 40149492, 2025). "Additionally, transwell and wound healing assays indicated that inhibition of MYOSLID in HCT15 colorectal cancer cells by applying siRNAs led to a substantially decreased ability to proliferate." (PMID 40149492, 2025). "MYOSLID knockdown has been reported to lead to a decrease in CD4+ T cells in colorectal cancer cells, which may play a role in regulating immunity to colorectal cancer." (PMID 39355236, 2024). "MYOSLID has been reported as a prognostic factor for colorectal cancer as a hypoxia-related lncRNA." (PMID 39355236, 2024). "Moreover, we validated the value of analysing the lncRNA MYOSLID, one of the hub lncRNAs in our model, which promotes colorectal cancer by regulating necroptosis." (PMID 36139524, 2022).
lymph node metastasis (1 paper, 2019). "Higher MYOSLID expression was related to advanced TNM stage and lymph node metastasis." (PMID 31238980, 2019).
osteoarthritis (1 paper, 2022). A noninflammatory degenerative joint disease occurring chiefly in older persons, characterized by degeneration of the articular cartilage, hypertrophy of bone at the margins and changes in the synovial membrane. "MYOSLID, which demonstrated the largest increase in high-osteoarthritis grade cartilage, is in a positive feedback loop with the transforming growth factor (TGF)-β/SMAD, a pathway involved in osteoarthritis development through regulation of articular chondrocyte hypertrophy and maturation." (PMID 35088088, 2022).
tumor (12 papers, 2019 to 2025). "Its multifaceted involvement in tumor biology makes MYOSLID a prospective diagnostic biomarker for early cancer detection and a potential target for therapeutic intervention." (PMID 40149492, 2025). "Further research suggests that MYOSLID promotes tumor cell proliferation and invasion, making it a hallmark of cancer and a defining factor in various cancer characteristics." (PMID 40149492, 2025). "MYOSLID is implicated in necroptosis, a programmed cell death, which is associated with tumor progression." (PMID 40149492, 2025). "The analysis of cancer-associated fibroblasts (CAFs) across multiple algorithms, including XCELL, TIMER, QUANTISEQ, MPCOUNTER, and EPIC, showed a strong positive correlation between risk scores and CAFs, suggesting MYOSLID promotes stromal remodeling to support tumor growth." (PMID 40149492, 2025). "By binding miR-29c-3p and preventing its interaction with MCL-1 at the 3′-UTR, MYOSLID disrupts the normal miRNA-mediated regulation of this oncogene, promoting tumor progression." (PMID 40149492, 2025). "Risk scores positively correlated with M0 macrophages and negatively with resting CD4 memory T cells, consistent with a tumor-promoting immune landscape influenced by hypoxia and MYOSLID-driven pathways." (PMID 40149492, 2025). "Among these, elevated levels of MYOSLID in various tumor tissues highlight its importance in the progression and pathogenesis of cancer." (PMID 40149492, 2025). "The results indicated that the MYOSLID expression was higher in most tumour samples than in non-tumor samples." (PMID 36139524, 2022). "We found that the size and weight of tumours in knockdown lncRNA MYOSLID group were significantly decreased compared with the empty vector group." (PMID 31497917, 2019). "We found for the first time that the expression of lncRNA MYOSLID was significantly up‐regulated in GC tissues, and the up‐regulation of lncRNA MYOSLID in GC was correlated with tumour size, AJCC stage, depth of invasion and survival time." (PMID 31497917, 2019). "Then, the expression of lncRNA MYOSLID in GC tissues was detected by real‐time PCR and found that the expression of lncRNA MYOSLID was higher in GC tissues than in matched non‐tumour tissues (n = 75, P < .0001)." (PMID 31497917, 2019). "By deepening our analysis of MYOSLID’s contributions to cancer pathogenesis, its regulatory effects on tumor microenvironments, and its involvement in critical cellular functions like metastasis and immune modulation, we can unlock new possibilities for early detection and intervention." (PMID 40149492, 2025). "Furthermore, hypoxia and lncRNA MYOSLID interact in a regulatory network that significantly contributes to tumor progression." (PMID 40149492, 2025). "Thus, induced MYOSLID expression suggests involvement in cancer cell survival, proliferation, and adaptation within hypoxia tumor microenvironments." (PMID 40149492, 2025). "Subsequently, the role of MYOSLID in tumour immunity was further investigated." (PMID 36139524, 2022). "In vitro and in vivo experiments demonstrated that after knockdown of lncRNA MYOSLID, cell proliferation and tumour growth were significantly inhibited and apoptosis was significantly increased, while overexpression of lncRNA MYOSLID promoted cell proliferation." (PMID 31497917, 2019). "These lncRNAs, LINC02428, STAG3L5P-PVRIG2P-PVRIG2P-PILRB, NSMCE1-DT, MYOSLID, MRPS9-AS1, NCBP2-AS1, WARS2-AS1, and LENG8-AS1, were found to be upregulated in tumor tissues." (PMID 40149492, 2025). "Targeting MYOSLID can potentially disrupt key mechanisms, such as EMT and immune evasion, thereby impairing tumor metastasis and progression." (PMID 40149492, 2025). "Researchers have identified numerous lncRNAs upregulated in tumor samples (CRC patients), including LINC02257, LINC02188, MYG1-AS1, C6orf223, L-SKA21, and MYOSLID." (PMID 40149492, 2025).
tumor (continued). "MYOSLID, known to promote EMT and tumor invasion, contributes to changes by influencing stromal activation and immune cell recruitment." (PMID 40149492, 2025). "The expression of LINC02257, LINC02188, MYOSLID, C6orf223, MYG1-AS1, and Lnc-SKA2-1 was upregulated in tumor samples, while the expression of LINC00702, LOC100129434, and LINC01915 was downregulated in tumor samples." (PMID 35846431, 2022). "Only four lncRNAs (LCMT1-AS1, MACORIS, MYOSLID, and ZEB1-AS1) were tested in the CC adjacent tissues and tumor tissues using qRT–PCR." (PMID 35237659, 2022). "Six of ten lncRNAs were differentially expressed between tumor and normal samples, including AL513318.2, AP003555.2, VIM-AS1, MYOSLID, AL137782.1, and AC073611.1." (PMID 36393968, 2022). "The results showed that MYOSLID, LINC00958, and AL022328.2 were expressed more, while AL450992.2 and AC068580.1 were expressed less, in tumor compared to normal tissues." (PMID 34660307, 2021). "The high expression of lncRNA MYOSLID is related to AJCC staging, tumour size and depth of invasion." (PMID 31497917, 2019). "The downregulation of MYOSLID correlates with increased immune cell infiltration, especially the elevation of CD4+ and CD8+ T cell populations, indicating its potential role in modulating the tumor immune microenvironment." (PMID 40149492, 2025). "Interestingly, knockdown of MYOSLID also increased the percentage of CD4+ and CD8+ T cells in subcutaneously transplanted tumours." (PMID 36139524, 2022).
cancer (10 papers, 2019 to 2025). A tumor composed of atypical neoplastic, often pleomorphic cells that invade other tissues. "Ultimately, MYOSLID has the potential to emerge as a reliable therapeutic target, offering innovative strategies to disrupt cancer progression and paving the way for innovative diagnostic tools and therapeutic strategies." (PMID 40149492, 2025). "In the long term, MYOSLID holds immense promise as a reliable target in the fight against cancer, with the potential to significantly improve patient outcomes and advance cancer treatment paradigms." (PMID 40149492, 2025). "Among the various hallmarks of cancer, invasion and metastasis are critical processes influenced by MYOSLID." (PMID 40149492, 2025). "MYOSLID is a well-established regulator of cancer progression, primarily through its role in stabilizing hypoxia-inducible factor 1-α (HIF1A)." (PMID 40149492, 2025). "MYOSLID is a significant lncRNA in the realm of cancer biology, so understanding its role is imperative." (PMID 40149492, 2025). "MYOSLID has emerged as a critical modulator in cancer progression by influencing key hallmarks such as proliferation, immune evasion, metastasis, and metabolic reprogramming." (PMID 40149492, 2025). "Cumulative studies, taken together, suggest that MYOSLID is the key regulator for sustained proliferative signaling in various cancer cells targeting miRNAs, hypoxia-related factors, and immune cells." (PMID 40149492, 2025). "Our focus is revealing MYOSLID’s multifaceted roles in cancer development, progression, and diagnosis." (PMID 40149492, 2025). "The suppression of MYOSLID significantly inhibited cancer cell activity and proliferation, corroborating findings from previous studies." (PMID 40149492, 2025). "MYOSLID drives cancer progression by disrupting critical signaling pathways that govern cell survival, proliferation, and metastasis." (PMID 40149492, 2025). "This review explores the role and clinical significance of a newly identified long non-coding RNA, MYOSLID, in cancer progression." (PMID 40149492, 2025). "The Kaplan–Meier survival analysis curve, which we have obtained, shows that MYOSLID expression levels were comparatively lower in HNSC (p = 0.00072) than in other carcinomas analyzed." (PMID 40149492, 2025). "Among the eight lncRNA signatures, MYOSLID, AC012073.1, and LINC00402 were associated with progression in various cancer types, but there is hardly any information reported on HCC." (PMID 36147735, 2022). "Using samples from clinical CRC patients, we observed that MYOSLID levels were higher in most cancer samples than in their paired pericarcinous samples." (PMID 36139524, 2022). "Six NETs-related lncRNAs (AF131215.5, MYOSLID, NKILA, AC090152.1, SNHG10, and TRG.AS) have been reported to be associated with cancer progression." (PMID 34257164, 2021). "Among lncRNAs displaying expression differences between PN and MES GSCs, we identified six lncRNAs associated with survival in GBM and other cancers: CTD-2589M5.5, MYOSLID, CRNDE, AC005264.2, SOX21-AS1 and RP11-575F12.1." (PMID 31969990, 2020). "GO and KEGG analyses revealed that MYOSLID was closely related to important biological processes and pathways that regulate cancer metastasis." (PMID 31238980, 2019). "The results showed that MYOSLID expression in the cancer group (0.01127 ± 0.01655) was higher than that in the adjacent cancer normal tissues (0.00299 ± 0.00608) (p = 0.037)." (PMID 31238980, 2019). "We detected MYOSLID expression in 15 paired fresh OSCC cancer tissues and adjacent normal tissues by RT-qPCR." (PMID 31238980, 2019). "Our results also demonstrated that inhibiting MYOSLID expression significantly inhibited cancer cell invasion and metastasis." (PMID 31238980, 2019). "The expression patterns of MYOSLID are often altered across various types of cancer." (PMID 40149492, 2025).
cancer (continued). "Therefore, in this study, we have discussed the mechanistic and regulatory roles of MYOSLID and uncovered the intricate connections in various cancers, as it is poised to serve as a promising emerging biomarker." (PMID 40149492, 2025). "In summary, MYOSLID may function in regulating the process of necroptosis and may also be involved in cancer immunity." (PMID 36139524, 2022). "MYOSLID may be a promising target for controlling cancer metastasis." (PMID 31238980, 2019). "Meanwhile, lncRNA MYOSLID in the DFS model was closely related to important biological processes and pathways that regulate cancer metastasis." (PMID 35069738, 2022). "In addition, KEGG pathway analysis highlighted the participation of MYOSLID target genes in cancer-related pathways such as chemical carcinogenesis through receptor activation, the TGF-β signaling pathway, and transcriptional misregulation in cancer." (PMID 40149492, 2025). "Additionally, MYOSLID drives metastasis by regulating epithelial–mesenchymal transition markers such as LAMB3 and Slug while promoting RAB13-mediated cytoskeletal remodeling and enhancing cancer cell invasion." (PMID 40149492, 2025). "Although the function of MYOSLID in epithelial cell types has not been explored, it is reasonable to speculate that MYOSLID expression in epithelial cells may also be related to the cancer cell differentiation program." (PMID 31238980, 2019).
MYOSLID also shares sentences with these, for which no sentence is quoted: human papillomavirus infection (1 paper); liver cancer (1); oral cell squamous carcinoma (1); stomach neoplasm (1).